PLSCR1 (phospholipid scramblase 1)
Description:
Catalyzes calcium-induced ATP-independent rapid bidirectional and non-specific movement of phospholipids (lipid scrambling or lipid flip-flop) between the inner and outer leaflet of the plasma membrane resulting in collapse of the phospholipid asymmetry which leads to phosphatidylserine externalization on the cell surface. Mediates calcium-dependent phosphatidylserine externalization and apoptosis in neurons via its association with TRPC5 (By similarity). Also exhibits magnesium-dependent nuclease activity against double-stranded DNA and RNA but not single-stranded DNA and can enhance DNA decatenation mediated by TOP2A. Negatively regulates FcR-mediated phagocytosis in differentiated macrophages. May contribute to cytokine-regulated cell proliferation and differentiation (By similarity). May play a role in the antiviral response of interferon (IFN) by amplifying and enhancing the IFN response through increased expression of select subset of potent antiviral genes. Inhibits the functions of viral transactivators, including human T-cell leukemia virus (HTLV)-1 protein Tax, human immunodeficiency virus (HIV)-1 Tat, human hepatitis B virus (HBV) HBx, Epstein-Barr virus (EBV) BZLF1 and human cytomegalovirus IE1 and IE2 proteins through direct interactions. Also mediates the inhibition of influenza virus infection by preventing nuclear import of the viral nucleoprotein/NP. Plays a crucial role as a defense factor against SARS-CoV-2 independently of its scramblase activity by directly targeting nascent viral vesicles to prevent virus-membrane fusion and the release of viral RNA into the host-cell cytosol. (Microbial infection) Acts as an attachment receptor for HCV.
Synonyms: MMTRA1B
Tractability: Antibody: UniProt places it where antibodies can reach, with high confidence; its Gene Ontology location is reachable by antibodies, with high confidence; UniProt predicts a signal peptide or a membrane-spanning region; the Human Protein Atlas places it where antibodies can reach. PROTAC: ubiquitination databases record sites on it; its protein half-life has been measured.
Gene: Protein-coding gene on chromosome 3 (146,511,858 to 146,544,862, reverse strand). Ensembl gene ENSG00000188313.
Subcellular location: Cell membrane; Nucleus; Cytoplasm; Cytoplasm, perinuclear region
Subcellular location (Human Protein Atlas): Golgi apparatus; Nucleoplasm; Plasma membrane
Gene Ontology:
Molecular function: calcium ion binding; CD4 receptor binding; DNA-binding transcription activator activity, RNA polymerase II-specific; enzyme binding; epidermal growth factor receptor binding; lead ion binding; magnesium ion binding; mercury ion binding; nuclease activity; phospholipid scramblase activity; protein binding; SH3 domain binding; virus receptor activity; zinc ion binding
Biological process: apoptotic process; defense response to virus; negative regulation of phagocytosis; negative regulation of viral genome replication; phosphatidylserine exposure on apoptotic cell surface; plasma membrane phospholipid scrambling; positive regulation of chromosome separation; positive regulation of DNA topoisomerase (ATP-hydrolyzing) activity; positive regulation of gene expression; positive regulation of innate immune response; positive regulation of transcription by RNA polymerase II; response to interferon-beta; response to lead ion; acute-phase response; phosphatidylserine biosynthetic process; platelet activation; regulation of Fc receptor mediated stimulatory signaling pathway; regulation of mast cell activation; symbiont entry into host cell
Cellular component: cytoplasm; cytosol; extracellular exosome; Golgi apparatus; membrane; membrane raft; nucleolus; nucleoplasm; nucleus; perinuclear region of cytoplasm; plasma membrane
Genetic constraint (gnomAD): Loss-of-function variants: 5 observed, 15.63 expected, observed/expected ratio (o/e) 0.32, 90% interval 0.17 to 0.67. The upper end of that interval is the gene's LOEUF score, 0.67, which puts it in group 2 of 6, group 1 being the genes least tolerant of losing a copy. Missense variants: 183 observed, 213.31 expected, observed/expected ratio (o/e) 0.86, 90% interval 0.76 to 0.97. Synonymous variants: 63 observed, 74.19 expected, observed/expected ratio (o/e) 0.85, 90% interval 0.69 to 1.05.
Homologues: Orthologues: chimpanzee PLSCR1 (99% identical), mouse Plscr1 (77% identical), rat Plscr2 (75% identical), pig PLSCR1 (71% identical), rat Plscr2 (67% identical), mouse Plscr2 (67% identical), dog PLSCR1 (66% identical), tropical clawed frog plscr1 (59% identical), Drosophila melanogaster scramb1 (54% identical), mouse Plscr1l1 (50% identical), tropical clawed frog plscr2 (50% identical), rat Plscr1l1 (48% identical), and 5 more. Paralogues in human: PLSCR2 (59% identical), PLSCR5 (47% identical), PLSCR4 (47% identical), PLSCR3 (47% identical).
Diseases named in the same sentence as PLSCR1 in open-access papers:
PLSCR1 is named in the same sentence as 64 diseases in open-access papers, as found by Europe PMC text mining. Sharing a sentence is not in itself a finding about the gene and the disease. The quoted sentences say what the papers report.
breast carcinoma (11 papers, 2015 to 2026). "Phospholipid scramblase 1 (PLSCR1) has been implicated in breast cancer progression, yet its precise role and underlying mechanisms in TNBC chemoresistance remain elusive." (PMID 42140933, 2026). "Because of the association of PLSCR1 with breast cancer aggressiveness, it was important to assess the possibility of PLSCR1 as a prognostic indicator for breast cancer patients." (PMID 32292520, 2020). "To explore the clinical implications of PLSCR1 expression for breast cancer progression, we first evaluated the association of PLSCR1 expression with tumor size in NKI295 and GSE7390 datasets." (PMID 32292520, 2020). "In this study, we show that PLSCR1 expression is significantly upregulated in basal-like breast cancer (BLBC), a subtype that is associated with large tumor size, high grade, metastasis, early recurrence, and poor survival 13-15." (PMID 32292520, 2020). "Having identified the critical roles of PLSCR1 in breast cancer, we determined the association of PLSCR1 expression with chemotherapy sensitivity in the GSE25066 dataset in which patients with breast cancer received chemotherapy including sequential taxane and anthracycline-based regimens." (PMID 32292520, 2020). "Because PLSCR1 was associated with tumor cell migration, invasion, and stemness, it might also be important for breast cancer metastasis." (PMID 32292520, 2020). "In our study, we demonstrated that several ISGs including IFITM1, STAT1 and PLSCR1 and their encoded proteins are constitutively overexpressed in AI-resistant breast cancer cells and AI-resistant tumors and that their overexpression provides a survival advantage in the resistant cells." (PMID 25588716, 2015). "Previous studies have reported that PLSCR1 can activate the STAT1 signaling pathway in breast cancer cells, suggesting a potential regulatory relationship." (PMID 41146421, 2025). "Expression and Tyr-phosphorylation of PLSCR1 is increased in basal-like breast cancer (BLBC) cells that facilitates its nuclear translocation." (PMID 35422844, 2022). "Analysis of STAT1 expression in different subtypes of breast cancer showed that, similar to PLSCR1, STAT1 was significantly upregulated in BLBC in the MEBTABRIC dataset." (PMID 32292520, 2020). "To explore potential molecular mechanisms of PLSCR1 in breast cancer, we investigated the correlation of PLSCR1 with other proteins." (PMID 32292520, 2020). "Analysis of the effect of PLSCR1 expression on breast cancer cell migration and invasion showed that knockdown of PLSCR1 expression markedly repressed the migration and invasion of MDA-MB231 and SUM159 cells." (PMID 32292520, 2020). "We first analyzed the effect of PLSCR1 expression on breast cancer cell proliferation, and found that knockdown of PLSCR1 expression caused a slight but significant decrease in MDA-MB231 and SUM159 cell proliferation." (PMID 32292520, 2020). "Co-expression analysis of PLSCR1 with other genes in a gene expression dataset (E-TABM-157) that contains 51 breast cancer cell lines showed that PLSCR1 expression positively correlated with STAT1 expression." (PMID 32292520, 2020). "Next, we investigated the clinical significance of IFITM1 and PLSCR1 expression in AI-resistant (recurrence) breast cancer by performing IHC staining on normal breast tissue, primary breast tumors (N = 40) and AI-resistant recurrence breast tumors (N = 40)." (PMID 25588716, 2015). "In the present study, we investigated the functional role of IFITM1 and PLSCR1 in AI-resistant breast cancer." (PMID 25588716, 2015). "We found that IFITM1 and PLSCR1 were constitutively overexpressed in AI-resistant MCF-7:5C breast cancer cells and AI-resistant tumors and that knockdown of IFITM1 significantly reduced their ability to proliferate, invade, and migrate." (PMID 25588716, 2015). "Relevantly, IFN-α promotes the nuclear translocation of PLSCR1 in breast cancer cells." (PMID 41439508, 2025).
breast carcinoma (continued). "PLSCR1 was found to activate the STAT signaling pathway in breast cancer." (PMID 41146421, 2025). "Conversely, PLSCR1 was reported to promote tumorigenesis in both breast cancer cells and colorectal carcinomas, indicating that the impact of PLSCR1 on cancer may differ depending on the type of cancer." (PMID 37893069, 2023). "Clinically, high PLSCR1 expression was strongly correlated with large tumor size, high grade, metastasis, chemotherapy resistance, and poor survival, indicating poor prognosis in breast cancer patients." (PMID 32292520, 2020). "These clinical validations support the critical role of PLSCR1 in breast cancer aggressiveness." (PMID 32292520, 2020). "Our study has also established that phosphorylation of PLSCR1 Tyr 69/74 plays an instrumental role in the proliferation and stemness of breast cancer cells by promoting its nuclear translocation, interaction with STAT3 and subsequent binding to the STAT1 promoter." (PMID 32292520, 2020). "PLSCR1 is highly induced by type 1 IFNs and it plays an antagonistic role in leukemia and ovarian cancer; however, its role in breast cancer is unknown." (PMID 25588716, 2015). "We found that IFITM1 and PLSCR1 were constitutively overexpressed in AI-resistant MCF-7:5C breast cancer cells and AI-resistant tumors and that siRNA knockdown of IFITM1 significantly inhibited the ability of the resistant cells to proliferate, migrate, and invade." (PMID 25588716, 2015). "Recently, we have reported several enzymes, such as fructose-1,6-biphosphatase (FBP1), urine diphosphate-galactose ceramide galactosyltransferase (UGT8) and phospholipid scramblase 1 (PLSCR1), were tightly correlated with breast cancer aggressiveness." (PMID 35526049, 2022). "To further verify the association of PLSCR1 with the basal subtype, we also examined PLSCR1 expression in five gene expression datasets (GSE12777, E-MTAB-181, GSE10890 and GSE16732) that contain 51, 56, 52 and 41 breast cancer cell lines, respectively 28-31." (PMID 32292520, 2020). "We then analyzed the expressions of PLSCR1, STAT3, and phosphorylated STAT3 (p-STAT3) in breast cancer cell lines and observed that PLSCR1 expression positively correlated with p-STAT3 expression." (PMID 32292520, 2020). "Consistently, PLSCR1 protein level was much higher in triple-negative breast cancer (TNBC), which mostly overlaps with BLBC, than in luminal subtype of breast cancers." (PMID 32292520, 2020). "Real-time PCR and Western blot analyses were used to assess mRNA and protein levels of IFITM1, PLSCR1, STAT1, STAT2, and IRF-7 in AI-resistant MCF-7:5C breast cancer cells and AI-sensitive MCF-7 and T47D cells." (PMID 25588716, 2015). "Previous studies have reported that IFITM1 and PLSCR1 exert both antiproliferative and proliferative effects in different types of cancer cells; however, their functional significance in AI-resistant breast cancer cells is not known." (PMID 25588716, 2015). "To understand better the role of the interferon signaling pathway in AI-resistant breast cancer we measured the basal expression of two well-known interferon stimulated proteins, IFITM1 and PLSCR1, in AI-resistant MCF-7:5C breast cancer cells and AI-sensitive MCF-7 and T47D cells." (PMID 25588716, 2015). "To determine the functional significance of IFITM1 and PLSCR1 in AI-resistant MCF-7:5C breast cancer cells, we transiently transfected MCF-7:5C cells with siRNA targeting IFITM1 or PLSCR1 and we assessed the effect of their knockdown on cell proliferation, cell death and cell cycle progression." (PMID 25588716, 2015). "For example, when stimulated with EGF, PLSCR1 not only directly binds to the promoter of STAT1, but also enhances STAT3’s binding to the STAT1 promoter in breast cancer cells, leading to the transactivation of STAT1 and basal-like breast cancer (BLBC) progression." (PMID 40248364, 2025).
viral infection (11 papers, 2018 to 2025). "In gene therapy, gene editing technologies can manipulate relevant genes in organoid models, knocking out phospholipid scramblase 1 (PLSCR1) to assess changes in susceptibility to viral infection, thereby informing the optimization of gene therapy strategies." (PMID 41359105, 2025). "This review aims to summarize the current understanding of PLSCR1’s multiple roles as a frontline defense against viral infections." (PMID 40248364, 2025). "With limited Ifn-λr1 expression, Plscr1-/- mice were unable to mount a robust type 3 IFN response to control early viral infection." (PMID 41439508, 2025). "Another key aspect that warrants further exploration is the relationship between PLSCR1 and apoptosis, particularly in the context of viral infections." (PMID 40248364, 2025). "PLSCR1 expression is potently induced by IFNs, whose central roles in initiating immune responses, especially during viral infections, are well established." (PMID 35650588, 2022). "As PLSCR1 is promptly induced following type I IFN signaling, and in turn contributes to maintaining this pathway active, it would be quite informative to monitor PLSCR1 activity throughout different phases of a viral infection." (PMID 35650588, 2022). "Human PLSCR1 expression is strongly induced in response to viral infection and either type I or type II IFN treatment (4, 18, –, 20)." (PMID 35138119, 2022). "We therefore investigated the possibility that PLSCR1 indirectly inhibits virus infection by stimulating the IFN pathway." (PMID 29352288, 2018). "Further investigations may elucidate the role of PLSCR1 in viral infection through its interaction with CBP." (PMID 35138119, 2022). "Human PLSCR1 expression has been shown to be induced in response to viral infection." (PMID 35138119, 2022). "The results show that ILDR1 expression is up-regulated after viral infection in Plscr1−/− mice, suggesting that ILDR1 might play a role in Influenza virus infection." (PMID 35595813, 2022). "To assess whether PLSCR1 blockade inhibits viral infection, we took advantage of the pharmacological scramblase antagonist, R5421." (PMID 29293671, 2018). "The results showed that WSN NP interacted with PLSCR1 during the natural viral infection." (PMID 29352288, 2018). "However, if PLSCR1 is co-opted by viruses to accelerate apoptosis and immunopathogenesis, it could facilitate viral propagation and viral infection-induced tissue damage." (PMID 40248364, 2025). "In addition, exploring the synergistic effects between emerging PLSCR1-based therapies and existing antiviral drugs could lead to the development of novel strategies, thereby improving our ability to combat current and future viral infections." (PMID 40248364, 2025). "PLSCR1 expression is induced in response to viral infection and IFN treatment, and PLSCR1 has been reported to play an important role in IFN-dependent antiviral responses." (PMID 35138119, 2022). "Human phospholipid scramblase 1 (PLSCR1) is strongly expressed in response to interferon (IFN) treatment and viral infection, and it has been suggested to play an important role in IFN-dependent antiviral responses." (PMID 35138119, 2022). "However, much detailed mechanism was not investigated and in our study, along with ASS1, there was an increased in E3 ubiquitin ligase deltex 3L, PLSCR1 and serpin were increased, which might be one of the antiviral effects induced by the host cell during the early stage of viral infection." (PMID 32566414, 2020). "PLSCR1, the most studied member of the phospholipid scramblase protein family, is one such ISG, with its expression highly induced by type 1, 2, and 3 interferons in various viral infections." (PMID 41439508, 2025). "Importantly, regardless of excessive production of antiviral IFNs in Plscr1-/- mice, they failed to effectively control the initial viral infection." (PMID 41439508, 2025).
viral infection (continued). "Additionally, PLSCR1 is identified as an interferon-stimulated gene (ISG) with antiviral activities, and its expression can be highly induced by all types of interferons in various viral infections." (PMID 40248364, 2025). "This work revealed that the basal expression of PLSCR1 in 36T-3 cells, which are human telomerase reverse transcriptase (hTERT)-immortalized human fibroblasts, was significantly higher than that in HEL cells in the absence of IFN treatment or virus infection." (PMID 35138119, 2022). "Importantly, the lipid scramblase activity of PLSCR1 has been shown to be dispensable for its anti-SARS-CoV-2 function in a similar manner, suggesting a general lack of significance for its enzymatic activity in viral infections." (PMID 41439508, 2025).